USP18 (ubiquitin specific peptidase 18)
Diseases named in the same sentence as USP18 in open-access papers (continued):
Sharing a sentence is not in itself a finding about the gene and the disease.
hepatocellular carcinoma (10 papers, 2011 to 2025). A malignant tumor that arises from hepatocytes. "Silencing of USP18 in hepatoma HepG2 cells was shown to cause accumulation of cells in G0/G1 and apoptosis." (PMID 30858391, 2019). "A previous report demonstrated that silencing USP18 suppressed proliferation and promoted apoptosis in hepatocellular cancer cells." (PMID 32770981, 2020). "It was observed that knockout of the USP18 gene in mouse embryonic fibroblasts and knockdown of USP18 expression in the human hepatoma cell line Huh7.5 lead to prolonged responsiveness to IFNα and enhanced antiviral efficacy against HCV." (PMID 32696599, 2020). "Moreover, the knockdown of USP18 in hepatoma cells was shown to potentiate the anti-HCV effect of IFN α." (PMID 21779393, 2011). "Thirdly, in hepatocellular carcinoma tissues, enzymes involved in the ISGylation process (including EFP, HERC5, UBA1 and USP18) are elevated compared with adjacent non‐tumour tissues." (PMID 36071546, 2022). "We establish, based on quantitative measurements obtained for the hepatoma cell line Huh7.5, an ordinary differential equation model for IFNα signal transduction that comprises the feedback regulators STAT1, STAT2, IRF9, USP18, SOCS1, SOCS3, and IRF2." (PMID 32696599, 2020). "In hepatoma cells, IFNL4 gene transfection or recombinant IFN-λ4 protein treatment robustly increased the protein levels of ISG15 and USP18 in an IFNLR1-dependent manner and potently blocked IFN-α signalling." (PMID 28630501, 2017). "Human hepatoma cells and primary murine hepatocytes were treated with TNF-α/LPS/IL-6/IL-10 and USP18, phosphorylated (p)-STAT1 and myxovirus (influenza virus) resistance 1 (Mx1) expression was determined." (PMID 27009955, 2016).
acute promyelocytic leukemia (7 papers, 2009 to 2024). An aggressive form of acute myeloid leukemia (AML), characterized by arrest of leukocyte differentiation at the promyelocyte stage, due to a specific chromosomal translocation t(15;17) in myeloid cells. "Conversely, USP18 repression has been associated with antineoplastic effects in lung and kidney cancers and in acute promyelocytic leukemia." (PMID 26555296, 2015). "The forced repression of USP18 is involved in the destabilization of cyclin D1 and promyelocytic leukemia/retinoic acid receptor α (PML–RARα), thereby leading to a reduction in proliferation and increased apoptosis." (PMID 32957626, 2020). "USP18 depletion has also been shown not only to reduce acute promyelocytic leukemia cell growth but also to induce apoptosis." (PMID 32957626, 2020). "USP18 overexpression is associated with augmented oncogene or growth factor receptor expression such as the epidermal growth factor receptor (EGFR) and tumor-promoting effects in acute promyelocytic leukemia, kidney and lung cancer." (PMID 26555296, 2015). "It is demonstrated that USP18 stabilizes PML/RARα protein and inhibits cell apoptosis in all-trans-retinoic acid (RA)-sensitive and RA-resistant acute promyelocytic leukemia (APL) cells." (PMID 34454635, 2021). "Besides our report, USP18 has been reported to directly maintain oncogene stability such as the chimeric, dominant-negative-acting transcription factor promyelocytic leukemia gene (PML)/RARa during acute promyelocytic leukemia development." (PMID 24884733, 2014).
autoimmune disease (7 papers, 2019 to 2025). A disorder resulting from loss of function or tissue destruction of an organ or multiple organs, arising from humoral or cellular immune responses of the individual to their own tissue constituents. "Humans deficient in USP18 or ISG15 develop severe autoimmune disease due to uncontrolled IFN-I signaling." (PMID 39969510, 2025). "It has been revealed that USP18 has multiple functions in the regulation of pathological processes, such as pathogen control, cancer development, autoimmune diseases, and neurological disorders." (PMID 34017322, 2021). "Significant overexpression of USP18 was observed in CD4+ T cells from SLE patients, indicating its role in the pathogenesis of autoimmune diseases." (PMID 31024609, 2019). "For example, USP18 and ISG15 are negative feedback regulators of IFNAR-JAK-STAT signaling, and their deficiency in humans drives severe autoimmune disease." (PMID 39969510, 2025). "Ubiquitin-specific protease 18 (USP18), also known as UBP43, is a member of the deubiquitinating (DUB) enzyme family and plays a pivotal role in various pathological conditions, including viral and bacterial infections, autoimmune diseases, neurological disorders, and tumor progression." (PMID 40514377, 2025).
bladder cancer (7 papers, 2021 to 2025). "Mechanistically, the lncRNA BCCE4 A allele loses a binding site for miR‐328‐3p, decreases USP18 expression levels by missing its function as a miRNA sponge, and thus downregulates PD‐L1 levels to restore the antitumour immune response in bladder cancer." (PMID 37705121, 2023). "These insights not only enhance our understanding of the genetic factors in bladder cancer but also open new avenues for the development of targeted therapies and diagnostic tools, particularly in the context of the PD-L1/PD-1 axis and its regulation by USP18." (PMID 38474186, 2024). "In bladder cancer, USP18 augments the removal of ISG15 from PD-L1, enhancing the stability of PD-L1." (PMID 38474186, 2024). "USP18 is upregulated in tumor tissues and contributes to the malignant phenotype of bladder cancer cells." (PMID 38474186, 2024). "A positive correlation was established between USP18 levels and PD-L1 expression in bladder cancer tissues." (PMID 38474186, 2024). "Subsequently, we observed that USP18 expression levels were markedly upregulated in bladder cancer tissues versus in normal tissues." (PMID 37705121, 2023). "Based on these cell models, we also determined that bladder cancer cells expressing BCCE4[A] had lower USP18 or PD‐L1 levels and exhibited less malignant behavior than those expressing BCCE4[G]." (PMID 37705121, 2023). "Consistent with these patient tumor-derived data, USP18 was also up-regulated in numerous bladder cancer cell lines." (PMID 33461172, 2021). "Posttranslational modifications, including the elevation of FTO protein levels in bladder cancer via USP18 deubiquitination, may also serve a pivotal function in the pathophysiological processes mediated by FTO." (PMID 39449798, 2024). "To confirm whether USP18 could be a target gene of miR‐328‐3p, we transfected a luciferase reporter vector harbouring the USP18 3′‐UTR into bladder cancer cell lines, and relative luciferase activity was then detected after miR‐328‐3p mimic transfection." (PMID 37705121, 2023). "Furthermore, we transfected USP18 overexpression plasmids into bladder cancer cell lines stably overexpressing BCCE4[A] and found that USP18 overexpression restored the tumor‐suppressing function of BCCE4[A]." (PMID 37705121, 2023). "Additionally, the FTO protein level was positively correlated with the expression of the deubiquitinase ubiquitin specific peptidase 18 (USP18) expression in bladder cancer." (PMID 35211409, 2022). "Furthermore, we performed correlation analysis in bladder cancer tissues and found that lncRNA BCCE4 levels exhibited a significant positive correlation with USP18 or PD‐L1 levels." (PMID 37705121, 2023). "Ubiquitin-specific peptidase 18 (USP18) upregulates FTO levels through post-translational deubiquitination while decreasing m6A levels in PYCR1, thereby stabilizing the PYCR1 transcript and promoting bladder cancer initiation and progression." (PMID 37391814, 2023). "In this study, we demonstrated that the post-translational deubiquitination by USP18 up-regulates the protein but not mRNA of FTO in bladder cancer tissues and cells." (PMID 33461172, 2021).
colorectal cancer (7 papers, 2015 to 2026). A primary or metastatic malignant neoplasm that affects the colon or rectum. "Meanwhile, western blot analysis revealed that USP18 protein expression was significantly higher in colorectal cancer tissues than in normal tissues." (PMID 32742193, 2020). "The result found that USP18 expression was higher in colorectal cancer tissues than in the paired normal tissues (P < 0.05)." (PMID 32742193, 2020). "In summary, USP18 expression in colorectal cancer tissues was higher than that in the paired normal tissues." (PMID 32742193, 2020). "qRT-PCR analysis indicated that USP18 expression was significantly higher in colorectal cancer tissues than in the paired normal tissues (P < 0.001)." (PMID 32742193, 2020). "USP18 is also highly expressed in colorectal cancer, where it regulates the oncogene Snail1 through the deubiquitination pathway, thus promoting the proliferation, colony formation, migration, and invasion of colorectal cancer cells." (PMID 40374599, 2025). "Moreover, we analyzed the distribution of the high USP18 expression in colorectal cancer tissues and the paired adjacent tissues." (PMID 32742193, 2020). "We demonstrated that high USP18 expression could be detected in colorectal cancer tissues and cells." (PMID 32742193, 2020). "This study was designed to investigate the role of USP18 in colorectal cancer." (PMID 32742193, 2020). "Furthermore, immunohistochemical staining analysis indicated that USP18 expression was significantly higher in colorectal cancer tissue than in the paired normal tissues (P < 0.001)." (PMID 32742193, 2020). "Furthermore, we studied the effect of USP18 and Snail1 on chemotherapy sensitivity of colorectal cancer." (PMID 32742193, 2020). "Overexpression of USP18 could promote proliferation, colony formation, migration, and invasion of colorectal cancer cells." (PMID 32742193, 2020). "USP18 could promote the proliferation, migration, and invasion of colorectal cancer by deubiquitinating and stabilizing the Snail1 protein in colorectal cancer." (PMID 32742193, 2020). "Usp18 inhibits Stat-signaling under physiological conditions in pancreatic beta-cells, but its role in colorectal cancer remains unknown." (PMID 25886253, 2015). "In this study, we examined PD-L1 expression in various types of immune cells in human colorectal cancer in connection to cancer progression-specific USPs, including USP10, USP12, USP14, USP18, USP32, USP33, and USP39." (PMID 41356798, 2026). "Within the colorectal cancer datasets (GSE108989, GSE139555, and GSE146771), USP18 was predominantly expressed in immune cells, fibroblasts, and malignant cells, particularly in CD8+ T cells." (PMID 39334957, 2024). "The same results were observed using the colorectal cancer cell line HCT116, suggesting an essential role for USP18 under an innate immune stimulation context, in different cancer cell types." (PMID 33214684, 2021). "However, whether USP18 could affect colorectal cancer through Snail1 remains unclear." (PMID 32742193, 2020). "USP18-dependent effects were explored further in CML and colorectal carcinoma cellular models." (PMID 33214684, 2021). "In this work, we investigated whether USP18 could regulate colorectal cancer cells migration and invasion in USP18 knockdown-treated SW480 cells and USP18 overexpression-treated DLD1 cells." (PMID 32742193, 2020).
glioblastoma (6 papers, 2020 to 2025). The most malignant astrocytic tumor (WHO grade IV). "Similar outcomes are obtained when USP18 is silenced in glioblastoma cells, which suggests that USP18 inhibition causes cells to undergo apoptosis with robust activation of caspase-8 and caspase-3 through enhancing the IFN-I pathway." (PMID 37658402, 2023). "Moreover, higher USP18 expression is closely associated with poor prognosis in glioblastoma patients, indicating the critical role of USP18 in glioblastoma progression." (PMID 32957626, 2020). "Furthermore, it has been reported that upregulation of USP18 in glioblastoma cell lines is associated with the resistance to TNF-related apoptosis inducing ligand (TRAIL)-induced apoptosis after IFNα challenge." (PMID 32957626, 2020). "Myc-tagged WT-SOX9 or different mutants were cotransfected with HA-Ub and Flag-USP18 into glioblastoma cells." (PMID 40374599, 2025). "We demonstrated in vitro that USP18/SOX9 plays a significant role in glioblastoma malignancy and the maintenance of stemness and explored its underlying mechanisms." (PMID 40374599, 2025). "Immunoprecipitation experiments revealed that USP18 knockdown significantly increased SOX9 ubiquitination in glioblastoma cells." (PMID 40374599, 2025). "Our study underscores the potential of targeting the YY1/USP18/SOX9 axis as a therapeutic strategy for glioblastoma." (PMID 40374599, 2025). "Both in vitro and in vivo experiments confirmed that USP18 promotes the stemness characteristics of GSCs and enhances malignant phenotypes such as proliferation, invasion, and migration in glioblastoma." (PMID 40374599, 2025). "Our results indicated that the knockdown of USP18 promoted the degradation of SOX9 in glioblastoma cells, thereby shortening its half-life." (PMID 40374599, 2025). "In this study, we demonstrated that USP18 is significantly upregulated in glioblastoma compared with normal brain tissue, particularly in GSCs, and is correlated with poor patient prognosis." (PMID 40374599, 2025). "For instance, downregulation of USP18 reduces acute promyelocytic leukaemia cell growth and induces apoptosis, whereas silencing USP18 in glioblastoma cells enhances IFN-induced apoptosis." (PMID 33051403, 2020). "Interestingly, USP18 associates with TWIST1 and mediates the stabilization of TWIST1, thereby leading to glioblastoma cell migration and invasion." (PMID 32957626, 2020). "Recently, it has been shown that the expression of USP18 is upregulated in glioblastoma." (PMID 32957626, 2020). "In MCF-7 cells and glioblastoma, knocking out USP18 can induce apoptosis of tumor cells." (PMID 32742193, 2020). "Through its USP domain, USP18 interacts with SOX9, stabilising the protein and thereby promoting the maintenance of glioblastoma stemness and the progression of malignant phenotypes." (PMID 40374599, 2025). "However, overexpression of USP18-C64S did not exert a similar effect on these glioblastoma cell lines." (PMID 40374599, 2025).
cardiac hypertrophy (5 papers, 2018 to 2025). "Both in murine experimental models and in humans, USP18 inhibits myocardial hypertrophy via the TAK1-p38-JNK1/2 axis upon an increased afterload." (PMID 38791035, 2024). "In brief, the authors observed that cardiomyocyte-specific overexpression of USP18 attenuated myocardial hypertrophy, fibrosis, ventricular dilatation, and ejection fraction decline induced by aortic banding, whereas USP18 knockout exacerbated remodeling." (PMID 38665231, 2024). "Overexpression of USP18 was shown to inhibit cardiac hypertrophy while its depletion amplified the hypertrophic response." (PMID 30186311, 2018). "Thus, further investigation of the role of the USP18 in inflammation in cardiac hypertrophy protection is another aspect that can be looked upon." (PMID 30186311, 2018). "Recently, accumulating evidence have confirmed the function of USP4, USP10, USP18, and USP25 in the regulation of pathological cardiac hypertrophy and remodeling, suggesting a possible involvement of the USP family in pathological cardiac remodeling." (PMID 38481817, 2024). "In vitro studies showed that USP18 knockout reduces the mRNA level of fetal genes such as ANP, BNP, and β-MHC, suggesting the protection of cardiac hypertrophy." (PMID 30186311, 2018).
chronic myeloid leukaemia (5 papers, 2009 to 2022). "For example, Kessler and co-workers used an advanced chemical proteomics approach identify a set of oncogenic substrates of USP18 that appeared to be more susceptible to irradiation, suggesting that selective inhibition of USP18 could sensitise chronic myeloid leukaemia patients to radiotherapy." (PMID 34497382, 2022). "In this study, using advanced proteomic techniques, we have significantly expanded the USP18-dependent ISGylome and proteome in a chronic myeloid leukaemia (CML)-derived cell line." (PMID 33214684, 2021). "In mouse model of chronic myelogenous leukemia-like myeloproliferative disease, USP18 has been demonstrated to play an important role in the regulation of latency and severity of leukemia development." (PMID 32957626, 2020). "We decided to study the effects of type I interferon α 2 (IFNa2; IFN hereafter) on human HAP1 cells, a chronic myeloid leukaemia (CML)-derived cell line, in the presence or absence of the USP18 gene." (PMID 33214684, 2021).
colon cancer (5 papers, 2015 to 2024). "Additionally, we observed a clear translocation of HMGB1 from the nucleus to the cytoplasm in Usp18+/- and Usp18-/- MC38 colon tumors, representing an ICD associated event in solid tumors." (PMID 38799433, 2024). "Thus, it is unclear if the high levels of Usp18 mRNA in shSep15 and shTR1 colon cancer cells support our results." (PMID 25886253, 2015). "Here, we provide an acute example of this phenomenon, whereby the early expression of USP18, post-interferon treatment of HCT116 colon cancer cells is sufficient to fully suppress the expression of the ISG15 E1 enzyme, UBA7." (PMID 37756534, 2023). "HCT116 colon cancer cells provide a striking illustration of the profound negative feedback effect exerted by USP18." (PMID 37756534, 2023).